TPO (thyroid peroxidase)
Diseases named in the same sentence as TPO in open-access papers (continued):
Sharing a sentence is not in itself a finding about the gene and the disease.
Graves disease (104 papers, 2001 to 2026). Graves' disease is an autoimmune disorder that leads to overactivity of the thyroid gland (hyperthyroidism).It is caused by an abnormal immune system response that causes the thyroid gland to produce too much thyroid hormones. "In comparison, natural aAb to another thyroid autoantigen, namely the thyroperoxidase (TPO-aAb), are detectable in both Graves’ disease and Hashimoto’s thyroiditis, where they are associated with cell-mediated cytotoxicity." (PMID 34884891, 2021). "The region is also associated with Graves' disease and thyroid peroxidase autoantibody positivity at rs11264798." (PMID 22526605, 2012). "Antibodies to thyroid peroxidase (TPO-Ab), measured using sensitive and standardized immunoassays, are elevated in more than 95% of patients with HT and nearly 85% of patients with Graves’ disease." (PMID 40927297, 2025). "Further workup revealed Graves’ disease (positive anti-thyroid peroxidase antibody results and elevated radioactive iodine uptake)." (PMID 41552243, 2025). "The patient was first admitted to endocrinology with thyrotoxicosis and positive results for anti-Tg and anti-TPO, and was diagnosed with Graves’ disease and concomitant nephrotic syndrome." (PMID 40076824, 2025). "Given the overlapping autoimmune pathophysiology between AIT and Graves’ disease (GD) or Graves’ orbitopathy (GO), some TPO SNPs have also been explored in these conditions." (PMID 40650076, 2025). "Tapering of immune suppression therapy after long-term islet allograft failure precipitated Graves’ disease only in T1D patients that were positive for thyroid peroxidase (TPO) autoantibodies at the time of induction therapy with Thymoglobulin." (PMID 39860427, 2025). "Firstly, the statistical power of our analyses varied across thyroid dysfunction phenotypes, with limited power to detect low to moderate effects of phenotypes such as hyperthyroidism, Graves’ disease, and TPO antibody positivity." (PMID 40722800, 2025). "The significance of thyroglobulin antibodies and thyroid peroxidase antibodies in Graves' disease remains equivocal." (PMID 38350897, 2024). "Other studies indicate that positive TPO-Ab and high Free triiodothyronine level in children with Graves' disease can be predictive factors for the presence of thyroid associated ophthalmopathy." (PMID 38350897, 2024). "Graves’ disease was diagnosed with elevated thyroid-stimulating immunoglobulins (TSIs) at 369% and thyroid peroxidase (TPO) antibodies at 567 IU/mL." (PMID 39130909, 2024). "Anti-TPO Abs: antithyroid peroxidase antibody, GD: Grave’s disease, OR: odds ratio, TED: Thyroid eye disease, ATD: antithyroid drugs." (PMID 37123800, 2023). "Anti-TPO Abs: antithyroid peroxidase antibody, GD: Grave’s disease, TED: thyroid eye disease, BMD: bone mineral density, ATD: antithyroid drug." (PMID 37123800, 2023). "In this study, a significant association was observed between patients who were hypothyroid while on ATD and those who were hypothyroid after Graves’ disease surgery with low titers of anti-TPO Abs." (PMID 37123800, 2023). "We performed a retrospective study of patients with Graves’ hyperthyroidism with known TPO Ab status, receiving the first administration of RAI." (PMID 35687484, 2022). "Graves' disease (GD) is a form of hyperthyroidism due to thyroid-stimulating hormone receptor autoantibodies (TRAb), and anti-thyroid peroxidase antibodies (anti-TPO antibodies)." (PMID 36514581, 2022). "All patients with TPO antibodies developed Graves' disease following discontinuation of immune suppression after graft failure vs. none of the TPO-negative recipients." (PMID 35903316, 2022). "Thyroid function tests revealed a biochemically hyperthyroid state with elevated anti-thyroid peroxidase antibodies and thyroid stimulating hormone receptor antibodies, findings consistent with Graves' disease." (PMID 36420235, 2022).
Graves disease (continued). "Future studies investigating pre-treatment parameters affecting the outcome after RAI in patients with Graves’ disease should incorporate TPO Ab status as a variable." (PMID 35687484, 2022). "A positive TPO Ab status was found in 69% of patients which is consistent with other studied cohorts of patients with Graves’ disease." (PMID 35687484, 2022). "FCRL3 has been associated with the production of cyclic citrullinated peptide autoantibodies in rheumatoid arthritis (RA) and antibodies to thyroid peroxidase in patients suffering from Graves’ disease." (PMID 28458671, 2017). "Hyperthyroidism with high level anti-thyroid peroxidase and diffusely uptake on thyroid scan confirmed the diagnosis of Graves' disease." (PMID 22308126, 2010). "In both diseases, there is a breakdown in tolerance and the generation of an immunoglobulin G response directed against thyrotropin receptor (predominantly in Graves' disease), thyroglobulin, and thyroid peroxidase (TPO)." (PMID 15769293, 2005). "More interestingly, mutation of the region 766–775 abrogated the binding of human anti-TPO aAbs from Hashimoto's and Graves' disease patients." (PMID 15769293, 2005). "In addition, we included autoimmune thyroid conditions (Hashimoto’s thyroiditis and Graves’ disease), as well as TPO antibody positivity, which is a biomarker of autoimmune thyroid disease." (PMID 40722800, 2025). "Furthermore, patients who had TPO autoantibodies developed Graves’ disease after discontinuation of immune suppressive therapy that followed Thymoglobulin induction therapy, suggesting that the immune system lost its capacity to suppress autoreactive T cells." (PMID 39860427, 2025). "Methimazole is the preferred therapy for adolescent hyperthyroidism, particularly in Graves’ disease, as it targets thyroid peroxidase to inhibit iodine oxidation and prevent the synthesis of thyroxine (T4) and triiodothyronine (T3); however, it does not deactivate circulating hormones." (PMID 41438458, 2025). "Screening for TPO-Ab may help detect autoimmune thyroid conditions, such as HT and Graves’ disease, even before clinical symptoms appear." (PMID 40927297, 2025). "While membranous nephropathy secondary to Graves’ disease is a rarely reported phenomenon, in a few prior documented cases renal biopsy stained positively for thyroglobulin and TPO, indicating that deposition of such in the kidney was responsible for the secondary membranous nephropathy." (PMID 37477245, 2023). "A similar finding was reported for proteolytic protein (PLP) involved in multiple sclerosis (MS) and thyroid peroxidase (TPO) involved in Grave’s disease where the antigenic peptides significantly differed for both endogenously and exogenously processed TPO proteins." (PMID 35222346, 2022). "Although direct food reactions did not occur with TSH-R and TPO most commonly associated with Graves' disease and Hashimoto's, there was significant cross-reactivity between both T4 and T3 hormones found within the thyroid gland with 25–35 food antigens." (PMID 28894619, 2017). "In addition to TRAbs, TPO and/or Tg antibodies are detectable in 25–75% of Graves’ disease patients, which is consistent with the lymphocytic infiltration seen in Graves’ thyroids and is typically less extensive than that seen for Hashimoto’s disease." (PMID 27895620, 2016). "Moreover, evidence suggests that only TSHR is the primary autoantigen of Graves’ disease, whereas immune responses to other thyroid antigens (e.g., Tg and TPO) simply reflect concomitant thyroiditis." (PMID 27895620, 2016). "Findings indicative of Hashimoto’s or Graves diseases were evaluated in 792 patients by testing for anti-thyroid peroxidase antibody, anti-thyroglobulin antibody, free thyroxine (T4), thyroid stimulating hormone (TSH) and/or TSH receptor antibodies and/or thyroid sonography." (PMID 25800473, 2015).
Graves disease (continued). "Forty-four human anti-TPO aAbs were selected from one "in cell" library and three random combinatorial libraries constructed from different B-cell subsets extracted from thyroid biopsies from Graves' disease patients." (PMID 15769293, 2005). "When expressed TPO displayed similar epitopes, to that of TPO from Graves' disease tissue." (PMID 11556840, 2001). "In the remaining 22 malignant thyroid tumours the TPO protein level varied considerably from normal to nearly absent when compared to normal thyroid tissue or tissues from patients with Graves' disease (range less than 0.5 to more than 12.5 μg mg−1 of protein)." (PMID 11556840, 2001). "Thyroid-specific genes are seen as interesting candidates, including primarily TPO and Tg genes in the case of AIT and TSHR genes in Graves’ disease (GD)." (PMID 38542286, 2024). "IID: intrathyroid injection of dexamethasone; GD: Graves’ disease; TSH: thyroid-stimulating hormone; FT4: free thyroxin T4; TGAb: thyrotrophin receptor antibody; TPOAb: thyroid peroxidase antibody; TGAb: thyroglobulin antibody." (PMID 32555990, 2020). "Other investigations revealed elevated anti-TPO and anti-TSH receptor antibodies consistent with Graves' disease." (PMID 20181115, 2010). "Additionally, thyroid-stimulating immunoglobulins (TSIs), thyrotropin receptor antibodies (TRAbs), and anti-thyroid peroxidase (anti-TPO) are assessed, as these antibodies are often elevated in Graves’ disease." (PMID 40364138, 2025). "Additionally, thyroid-stimulating immunoglobulins (TSIs), thyrotropin receptor antibodies (TRAbs), and anti-thyroid peroxidase (anti-TPO) are evaluated, and these antibodies are often elevated in Graves’ disease." (PMID 38397367, 2024). "In patients with Graves’ hyperthyroidism, TPO Ab status is neither routinely evaluated during the diagnostic workup nor measured to guide management." (PMID 35687484, 2022). "Despite the fact that determination of the TPO Ab titer is currently not required for the diagnosis of Graves’ disease, we observed that it was measured at diagnosis in 71% of patients." (PMID 35687484, 2022). "Excluded were patients <18 years old, with sonographic features of HT but negative thyroid peroxidase (TPOAbs) or thyroglobulin autoantibodies (TgAbs), Graves’ disease, Down or Turner’s syndrome." (PMID 35528009, 2022). "The thyroid peroxidase antibody test and thyroglobulin antibody test used in that study are not specific for the diagnosis of Graves disease." (PMID 26962803, 2016). "These antibodies are less common but still frequent in Graves' disease, whereas TPO rather than TG antibodies are frequent in postpartum thyroiditis." (PMID 23878745, 2013). "In addition to the thyroid scan findings, the presence of clinical features, elevated anti-TPO antibodies, and initial TFTs supports the diagnosis of Graves’ disease and reinforces an autoimmune process rather than nodular pathology." (PMID 40772166, 2025). "Gender, age, BMI, and family history of thyroid disease could not be assessed to predict the positivity of anti-TPO Abs in patients with Graves’ disease." (PMID 37123800, 2023). "Graves’ disease is a common AITD with variable clinical courses as well as the production of a high number of antibodies, of which anti-TPO Abs depict no established clinical significance." (PMID 37123800, 2023). "Unlike autoantibodies to thyroglobulin (Tg) or thyroid peroxidase (TPO), thyroid-stimulating TSHR autoantibodies are not just a marker of Graves’ disease but are also held directly responsible for the hyperthyroidism that occurs in most of the patients." (PMID 27895620, 2016). "The TSHr-Ab assay has therefore to be considered as a useful tool to reveal subclinical autoimmune hyperthyroidism whenever TSH is below the normal range, even if TPO-Abs are negative and there is no other sign of endocrine autoimmunity." (PMID 22654905, 2012).
Autoimmunity (102 papers, 2011 to 2026). The occurrence of an immune reaction against the organism's own cells or tissues. "The combination of high anti-TPO-IgG and low IgE levels was shown to exist in association with other markers of autoimmunity such as ASST and BAT, suggesting that all these markers should be included in the prediction of CSU severity, and prognosis." (PMID 40546743, 2025). "Prolonged digital engagement and anti-TPO antibody positivity were identified as key risk factors, suggesting a role for occupational exposures and autoimmunity in early thyroid dysfunction." (PMID 40671987, 2025). "In summary, the majority of hypothyroid subjects demonstrated evidence of autoimmunity, with anti-TPO positivity strongly associated with both female gender and the presence of additional autoimmune conditions, particularly celiac disease." (PMID 41280993, 2025). "A significant number of SCH with high anti-TPO antibody titer points towards autoimmunity as being a significant cause of the decreased level of thyroid hormones in pregnancy." (PMID 35165548, 2022). "The inverse relationship observed between baseline CD4 count and anti-TPO antibody titers raises the possibility of increased immunodeficiency early in the course of disease being linked to increased occurrence of autoimmunity later." (PMID 26798547, 2015). "While elevated TPO antibodies are frequently observed, a direct causal relationship with HE is unlikely, and their presence may indicate a general state of autoimmunity." (PMID 40149702, 2025). "While elevated TPO antibodies are frequently observed, their direct causal relationship with HE is unlikely, and their presence may merely indicate a general state of autoimmunity." (PMID 40149702, 2025). "It is worth noting that previous studies have shown that the detection of thyroid peroxidase antibody (anti‐TPO) is useful in patients with subclinical hypothyroidism because the presence of anti‐TPO confirms that autoimmunity is the cause of subclinical hypothyroidism." (PMID 33817980, 2021). "Thyroidectomy was associated with a marked fall in TPO antibody levels but there are several pathways by which autoimmunity could theoretically produce such effects besides one which is antibody-mediated, most obviously via cytokines." (PMID 33332019, 2021). "A number of these patients have likely non-pathogenic antibodies to antigens such as glutamate decarboxylase (GAD) and Thyroid peroxidase (TPO) which may represent an underlying tendency to autoimmunity." (PMID 31552027, 2019). "First, anti-TPO antibody testing should be routinely considered in the evaluation of hypothyroid patients, as it not only establishes the autoimmune etiology but also identifies patients who may be at risk of developing other autoimmune conditions." (PMID 41280993, 2025). "However, it is unclear whether the autoimmunity related to elevated TPO-Ab or Tg-Ab was associated with the severity of AIS." (PMID 35256895, 2022). "Anti-TPO positivity was associated with higher TSH levels and elevated hsCRP, suggesting a link between autoimmunity and systemic inflammation." (PMID 39902025, 2025). "Anti-TPO IgG and/or IgE antibodies suggest autoimmunity, which represent different phenotype/endotypes but can overlap, and are associated with more prolonged disease." (PMID 40546743, 2025). "Our study adds to this body of evidence by demonstrating that hsCRP elevation is significantly correlated with TSH and anti-TPO levels (r = 0.62 and r = 0.58, respectively), suggesting a direct link between thyroid dysfunction, autoimmunity, and inflammation." (PMID 39902025, 2025). "There was also a statistically significant positive correlation between autoimmunity (TPO-Ab and TG-Ab) and BMI." (PMID 40137106, 2025). "Looking into this group, we were able to find a higher percentage of autoimmunity, namely, the presence of autoimmune disorders and anti-TPO antibodies and a higher prevalence of low levels of IgE." (PMID 39416263, 2024).
Autoimmunity (continued). "Among the 23 PH patients, 60.9% (14 patients) demonstrated some degree of autoimmunity with at least a positive TPO and/or Tg antibody; two patients were additionally TBII-positive and one patient was also TSI-positive." (PMID 37168978, 2023). "During the early stages of autoimmunity, the main detrimental effects comprise the hostile immune environment impacting the ovary, with TPO as the direct antigen." (PMID 35351031, 2022). "The present study illustrated deranged thyroid status and increased anti-TPO in 19.8% and 17.1% of psoriasis patients, respectively, suggesting thyroid dysfunction and autoimmunity." (PMID 35415048, 2022). "From the perspective of autoimmunity, several previous studies have assessed anti-thyroid peroxidase (TPO), anti-thyroglobulin (Tg), and anti-nuclear antibodies in patients with SAPHO syndrome." (PMID 33392854, 2021). "Evidence for autoimmunity markers (positive anti-thyroid peroxidase antibodies, anti-nuclear antibodies or AutoST) was found in 45.2% (n = 19) of 42 tested patients." (PMID 33292453, 2020). "We conclude that the enhanced thyrocyte lysis resulted from the higher anti-TPO content in the whole IgG pool of HT donors and from altered IgG glycosylation in HT autoimmunity." (PMID 31979029, 2020). "It is now well established that GD, B, and T lymphocyte-mediated autoimmunity are known to be directed against four well-known thyroid antigens: thyroglobulin (Tg), thyroid peroxidase (TPO), sodium-iodide symporter (NIS) and the thyrotropin receptor (TSH-R)." (PMID 29449887, 2018). "In conclusion, we demonstrate that anti-TPO can potentially indicate longer CSU disease duration while autoimmunity in CSU can predict disease severity and therapeutic response." (PMID 30515422, 2018). "In humans, and in mice that spontaneously develop autoimmunity to all three thyroid autoantigens, autoantibodies develop first to Tg and later to TPO and the TSHR A-subunit." (PMID 29326719, 2017). "Based on the literature, autoantibodies were also tested against six potential organ–specific antigens implicated in T1D and/or other autoimmune conditions including ATP4B, TGM2, TPO, KCNRG, AQP-4, and GFAP." (PMID 23028856, 2012). "Her serum anti-TPO antibodies were still elevated when she was discharged and had persisted for a year after dismissal, which suggested a propensity for autoimmunity in anti-NMDAR encephalitis." (PMID 22126669, 2011). "Type I autoimmunity involves autoreactive IgE antibodies targeting self-antigens such as thyroid peroxidase (TPO), interleukin-24 (IL-24), thyroglobulin, and tissue transglutaminase, leading to mast cell and basophil degranulation via classical IgE–FcεRI signaling pathway." (PMID 41608596, 2026). "In support of the persistent autoimmunity hypothesis, a systematic review showed that thyroid peroxidase antibodies were found to correlate with persisting symptoms in 16 of 23 studies analysed." (PMID 40366247, 2025). "Second, mild elevation of anti-GAD and anti-TPO antibodies in the serum is unlikely to be the cause of the disease but was considered a marker of autoimmunity." (PMID 38887352, 2024). "The study findings reinforce the hypothesis of a link between advanced liver steatosis and subclinical hypothyroidism, potentially mediated by autoimmunity – particularly subclinical hypothyroidism with positive anti-TPO antibodies – and independent from BMI." (PMID 39420912, 2024). "More recently, autoantibodies against Dsc1 and Dsc3, mitochondrial proteins, human leukocyte antigens, molecules, thyroid peroxidase (TPO), a Ca2+/Mn2+-ATPase encoded by ATP2C1 (hSPCA1), and several muscarinic and nicotinic AChRs have been identified as novel targets for pemphigus autoimmunity." (PMID 36979046, 2023). "However, when this tolerance is broken, autoimmunity occurs, resulting in the production of autoantigens such as thyroid peroxidase (TPO), thyroglobulin (Tg) and thyroid-stimulating hormone (TSH) receptor (TSH-R)." (PMID 36835987, 2023).